LASP1 (LIM and SH3 protein 1)
Diseases named in the same sentence as LASP1 in open-access papers (continued):
Sharing a sentence is not in itself a finding about the gene and the disease.
cancer (continued). "The various conclusions might be explained by that the LASP-1 gene expression could be regulated by different molecular mechanisms in cancer cell lines and stem cells." (PMID 22897902, 2012). "However, only LASP-1 seems to participate significantly in neuronal differentiation and plays an important functional role in migration and proliferation of certain cancer cells while the role of LASP-2 is more structural." (PMID 18419822, 2008). "Expression induction required the activation of the PI3-kinase signalling pathway, suggesting that LASP-1 may mediate IGF-IR function in cancer progression and operates as a signal transducer." (PMID 18419822, 2008). "Anti-WNT1 monoclonal antibodies show promising in vitro effects in cancer treatment, maybe mediated through down regulation of LASP-1 and other proteins enhancing anchorage independent migration." (PMID 18419822, 2008). "Two additional observations underscore the importance of LASP-1 in cancer." (PMID 17211471, 2007). "Knockdown NFE2L3 or LASP1 restored the changes in cell proliferation and migration caused by overexpression of NAT10, indicating that NAT10 might perform similar functions through NFE2L3/LASP1 signalling in other cancers." (PMID 40169553, 2025). "Moreover, LASP1 overexpression contributes to the aggressiveness of cancer cells." (PMID 39449799, 2024). "Furthermore, LASP1 has previously been shown to be regulated by several miRNAs in diverse cancers." (PMID 38789663, 2024). "Furthermore, both the SH3 and LIM domain play a role in regulating actin dynamics, suggesting LASP1 may have roles in other cellular processes deregulated in cancer cells." (PMID 38789663, 2024). "Currently, it is known that LASP1 is a multidomain protein that interacts with various proteins, that it is able to exert different roles in cell signalling and in transcriptional regulation, and that it is also able to activate survival and proliferation pathways in different cancer types." (PMID 36672776, 2022). "Finally, the novel functional roles of LASP1 in secretion of vesicles, expression of matrix metalloproteinases and transcriptional regulation as well as the activation of survival and proliferation pathways in different cancer types are described." (PMID 30298118, 2018). "However, nuclear accumulation of Lasp1 is observed in diverse cancer entities." (PMID 29088849, 2017). "Moreover, current clinical studies suggest that over-expression of LASP-1 could serve as a prognostic marker and is correlated with increased clinical stage, lymph node metastasis, and poor survival of cancer patients." (PMID 28266596, 2017). "The mechanism by which LASP-1 affects cancer cell proliferation and migration remains unclear." (PMID 24955835, 2014). "LASP1 is required for the proliferation and invasive phenotype of HPV+ cancer cells in vitro in an SH3-dependent manner, but is less important in HPV negative (HPV-) cancer cells." (PMID 38789663, 2024). "Our findings suggest that LASP1 plays a key role in HPV-induced oncogenesis, highlighting a potential therapeutic target in these cancers." (PMID 38789663, 2024). "In large B-cell lymphoma (DLBCL), miR-665 has been shown to suppress the growth of cancer cells by targeting MYC and LASP1." (PMID 37894282, 2023). "The LIM and SH3 domain protein 1 (LASP1) was originally identified in metastatic breast cancer and mainly characterized as a cytoskeleton protein overexpressed in various cancer types." (PMID 36672776, 2022). "The lncAMPC/miR-637/LIF axis in PCa, HOTTIP/miR-637/LASP1 axis in CHOL, LOC646616/miR-637 axis in essential hypertension, exert oncogenic effects in cancer." (PMID 36175921, 2022).
cancer (continued). "Cancer cell invasion ability was significantly increased by TGF-β1, whereas it was attenuated by LASP1 silence or further enhanced by overexpression." (PMID 34912481, 2021). "The miR-203 target LIM and SH3 protein 1, LASP1, is a nucleo-cytoplasmic shuttle protein involved in migration, adhesion, proliferation, and cell cycle progression in a variety of cancers." (PMID 34449670, 2021). "Although the exact biological function of LASP1 is still ambiguous, the activation of PI3K/AKT, MAPK, and Smad signaling pathways by LASP1 in cancer progression has been elucidated." (PMID 30988074, 2019). "However, LASP1 was not confined to metastasis and LASP1 also affects cancer proliferation and may be associated with the drug response." (PMID 29980193, 2018). "More recently, it has been shown that up-regulation of LASP1 created aggressive phenotypes of ESCC, thereby promoting cancer growth and metastasis." (PMID 28404954, 2017). "LIM and SH3 protein 1 (LASP1), a promoter of cell proliferation and migration, play a significant role in cancer development and progression." (PMID 28651018, 2017). "The present data provide an important clue on the pathophysiological role of LASP1 on MMP regulation and hence metastasis in aggressive cancer cells." (PMID 27588391, 2016). "Introduction of LASP1 induced EMT process and created aggressive phenotypes of cancer cells, thereby promoting cancer growth and metastasis." (PMID 27181092, 2016). "In our in vitro studies the use of confocal immunofluorescence displayed the nuclear localization of LASP-1 both in normal human fibroblasts and in HCC derived cells, but at higher level in cancer cells as expected." (PMID 25760690, 2015). "However, whether LASP1 is modulated by HPV or in HPV-associated cancers is currently not known." (PMID 38789663, 2024). "It is considered that the ternary complex of LASP1, CERS6, and actin may contribute to lamellipodia formation and cancer cell migration." (PMID 37345118, 2023). "Together, these results suggest that CERS6 and/or C16 ceramide are required for the formation of a complex between LASP1 and β actin, and that CERS6 may form a ternary complex resulting in efficient lamellipodia formation and cancer cell migration." (PMID 37345118, 2023). "Moreover, LASP1 has been reported to induce the EMT process and create aggressive cancer cell phenotypes, which thereby promotes cancer cell growth and metastasis." (PMID 33074595, 2020). "Among them, we selected the actin-binding protein gene ANLN because our past studies showed that several actin-binding protein genes (CORO1C, FSCN1,LASP1 and MSN) were overexpressed in cancer tissues and were deeply involved in promoting human cancer cell migration and invasion." (PMID 28881803, 2017). "LIM and SH3 domain protein (LASP-1) is responsible for the development of several types of human cancers via the interaction with other proteins; however, the precise biological functions of proteins interacting with LASP-1 are not fully clarified." (PMID 28266596, 2017). "Our study provides the first evidence of the newly identified PVT1/miR-203/LASP1 axis in carcinogenesis and metastasis of ESCC and may serve as a candidate target for cancer therapy." (PMID 28404954, 2017). "Consistently, we detected an opposite distribution and function of LASP1 and LASP2 in CRC, which may be a part of the regulation networks in cancer progression." (PMID 28606091, 2017). "However, further works need to be done as to the interaction of LASP1 and LASP2, and we still have a long way to go to better understand the whole frame of cancer metastasis." (PMID 28606091, 2017). "Consistently, LASP1 overexpression in the non-cancer PTK-2 cell line, which does not express endogenous LASP1, resulted in a significant increase in cell motility." (PMID 25622104, 2015).
cancer (continued). "Collectively, these observations suggest that LASP1 overexpression in multiple cancers is not a mere passenger event, but rather a driver of tumorigenesis and cancer progression." (PMID 25622104, 2015). "In addition, gene transfection-mediated LASP-1 overexpression in SW480 CRC cells resulted in aggressive cancer cells and promoted cancer growth and metastasis." (PMID 24955835, 2014). "This nuclear staining is unlikely to be unspecific, because nuclei of other benign stromal cells like fibrocytes are LASP-1-negative, even when located right next to cancer cells." (PMID 17956604, 2007). "Immunohistochemistry clearly allowed to localize LASP-1 expression in carcinoma cells of 76 malignant breast carcinomas (91.56 %), whereas in seven patients LASP-1 could not be detected in invasive neoplastic cells." (PMID 17956604, 2007). "In the present study, we also demonstrated that 14-3-3ơ could interact with AKT and counteract LASP1-dependent activation of AKT kinase in CRC aggressiveness, suggesting 14-3-3ơ as a molecular regulator of AKT and as a potential anticancer agent for AKT-activated cancers." (PMID 27156963, 2016). "In ESCC, expression of miR-203 in cancer tissues is remarkably lower than that in nontumorous tissues and miR-203 suppressed migration and invasion of ESCC cells via downregulation of LASP1." (PMID 28404954, 2017). "For cancer related death (CRD), we failed to attend significance between cytosolic LASP1 levels and this parameter (p=0.1)." (PMID 24980827, 2014). "In recent years, using a proteomics analysis, we found that LASP-1 is a mediator of uPA during migration of HCC cells and that LASP-1 expression is coordinated with the overexpression of uPA, a negative prognostic marker for this type of cancer." (PMID 25760690, 2015). "Although LASP-1 sequence analysis revealed no nuclear localisation signal, the classical import pathway for the nucleus, LASP-1 binds to the well-characterised shuttle proteins and transcription factors LPP and Zyxin that are upregulated in a wide variety of human cancers." (PMID 20461080, 2010).
infection (2 papers, 2016 to 2023). The state of being infected such as from the introduction of a foreign agent such as serum, vaccine, antigenic substance or organism. "Specifically, infection with hepatitis B virus X increased LASP1 expression and led to cell migration." (PMID 27709125, 2016). "Four additional infection-induced proteolytic cleavage sites identified in BCAP31, LASP1, MISP, and TRIM28 were consistent with the sequence specificity of 3CLpro." (PMID 37240067, 2023). "This point is exemplified by our identification of the infection-induced proteolysis of BCAP31 and LASP1 from the detection of neo-C-termini." (PMID 37240067, 2023).
adenocarcinoma (1 paper, 2016). A common cancer characterized by the presence of malignant glandular cells. "Increased protein levels of HYOU1, EPRS and LASP1 in NSCLC adenocarcinoma was independently validated by tissue microarray immunohistochemistry." (PMID 27799870, 2016). "Notably, adenocarcinoma abundance of LASP1 was only significantly higher relative to control tissue in those subjects who died." (PMID 27799870, 2016). "Additionally, TMA results indicated that most adenocarcinoma cases revealed low expression of LASP1 immunostaining (18/23, 78.2%)." (PMID 27799870, 2016). "Three top candidate proteins, EPRS, HYOU1 and LASP1 from the discovery study were independently validated with a tissue microarray containing 40 pairs of malignant and non-malignant tissues from patients with early stage NSCLC adenocarcinoma." (PMID 27799870, 2016).
vascular disorder (1 paper, 2020). A general term used to describe any disease affecting blood vessels]. "Five proteins, THBS2, LASP1, LAMB3, ITGAV, and COL11A1A, were selected according to their GO classification, the Kyoto Encyclopedia of Genes and Genomes (KEGG) pathways in which they can be involved and their relationship with AAA or vascular disorders." (PMID 32605321, 2020).
LASP1 also shares sentences with these, for which no sentence is quoted: Fibroadenoma (3 papers); papillary thyroid cancer (3); squamous cell carcinoma (2); stomach cancer (2); Acute hepatitis (1); acute lymphoblastic leukemia (1); adenomyosis (1); bipolar disorder (1); breast cancer disease (1); diabetes (1); Digestive Diseases (1); digestive system tumour (1); dysplasia (1); gallbladder cancer (1); head and neck cancer (1); intrahepatic cholangiocarcinoma (1); kidney cancer (1); liver cirrhosis (1); meningioma (1); metastatic prostate carcinoma (1); myocardial infarction (1); Nephropathy (1); neurological diseases (1); Obesity (1); oral squamous cell carcinoma (1); ovarian tumor (1); psoriasis (1); rectal cancer (1); retinoblastoma (1); serous ovarian cancer (1).
A further 3 diseases each share a sentence with LASP1 in 1 paper.